HOTAIR (HOX transcript antisense RNA)
Diseases named in the same sentence as HOTAIR in open-access papers (continued):
Sharing a sentence is not in itself a finding about the gene and the disease.
breast cancer (continued). "It should be also noted that our ERα-dependent lncRNA set does not contain most of the lncRNAs that were previously studied in breast cancer, such as HOTAIR, CCAT2, UCA1, MALAT1, BCAR4, EGOT, SPRY4-IT1 and others." (PMID 26621851, 2016). "The novelty of our work resides in the identification of a new estrogen-dependent association between HOTAIR/MALAT1 and ERβ/ERα (in prostate or breast cancer cells, respectively) and/or eNOS." (PMID 27922078, 2016). "Bisphenol-A and diethylstilbestrol exposure induced alterations in the expression of the lncRNA, HOTAIR, in cultured human breast cancer cells (MCF7) as well as in the mammary glands of rats." (PMID 26908441, 2016). "ER is still recruited to chromatin in tamoxifen-resistant breast cancer, further binds to the HOTAIR promoter region and enhances transcription of the HOTAIR gene, thus promoting breast cancer growth." (PMID 27897214, 2016). "The novel function of rs920778 on HOTAIR was further confirmed in other cancer, including colorectal cancer, gastric cancer, and breast cancer." (PMID 26934323, 2016). "One of the first evidence of lncRNA involvement in cancer progression has been reported in breast cancer, where HOTAIR expression was being systematically increased compared to normal tissue." (PMID 27340923, 2016). "HOTAIR reprograms chromatin stage and gene expression to promote invasion and metastasis in breast cancer." (PMID 27409175, 2016). "HOTAIR is shown to promote breast cancer metastasis by reprograming chromatin state, and HOTAIR expression level has prognostic value for metastasis and survival." (PMID 27833134, 2016). "Our study showed the effective chemopreventive effects of Dp on chemical carcinogen-induced breast carcinogenesis, and we found that Dp down-regulated HOTAIR expression by suppressing Akt activation in breast carcinogenesis and breast cancer cells." (PMID 27388461, 2016). "In conclusion, this study suggests that the lncRNA MALAT1 (as the well-known lncRNA HOTAIR) is involved in breast cancer." (PMID 27172249, 2016). "The cell viability assay further revealed that the up-regulation of HOTAIR significantly decreased the cytotoxic effects of Dp on breast cancer cells." (PMID 27388461, 2016). "Confirming previous observations, the expression levels of HOTAIR in cervical cancer cell lines, SiHa, HeLa and Caski cells were significantly higher than breast cancer cells MCF-7 and human embryonic kidney cells 293T as references." (PMID 27467165, 2016). "As one of the well-studied lncRNAs, studies have shown that disruption of lncRNA HOTAIR action occurs in different cancer types, such as lung cancer, breast cancer and nasopharyngeal carcinoma." (PMID 27467165, 2016). "Studies showed that HOTAIR is aberrantly up-regulated in many cancers, including breast cancer, colorectal cancer, and prostate cancer." (PMID 27388461, 2016). "To explore the mechanism by which Dp down-regulates HOTAIR expression, we investigated the effects of Dp on Akt activation in breast carcinogenesis and breast cancer cells." (PMID 27388461, 2016). "In contrast, high HOTAIR expression had lower risks of relapse and mortality than those with low HOTAIR expression through 336 breast cancer patients." (PMID 26942882, 2016). "The miR-148a level in the cancer tissues from the breast cancer patients was also negatively correlated with the HOTAIR level (R2 = 0.6251, P < 0.001)." (PMID 25928008, 2015). "From clones with various levels of HOTAIR overexpression, we used mostly those with the highest levels to mimic HOTAIR expression in breast cancer." (PMID 25994132, 2015). "Recently, the up-regulation of HOTAIR was observed in several cancers, including breast cancer, hepatocellular carcinoma, colorectal cancer (CRC), pancreatic cancer, non-small cell lung cancer (NSCLC) and esophageal squamous cell carcinoma (ESCC)." (PMID 25928008, 2015).
breast cancer (continued). "Consistent with our results, HOTAIR is over-expressed in early and metastatic breast cancer cells, serves as a prognostic factor for glioma patient and promotes glioblastoma cell cycle progression in an EZH2 dependent manner." (PMID 26183397, 2015). "Downregulated HOTAIR showed an anti-correlative relationship with both HOXD10 and miR-7 in MDA-MB-231 breast cancer cells and miR-7 was inversely correlated with HOTAIR expression in breast cancer patients." (PMID 26308064, 2015). "HOTAIR promotes metastasis of breast cancer cells and its over-expression was correlated with poor prognosis of breast cancer patients." (PMID 26378045, 2015). "We found that E2 up-regulated HOTAIR in breast cancer cells through GPER via the suppression of miR-148a." (PMID 25928008, 2015). "By comparing background genes and DCGs with a list of genes bound to PRC2 after HOTAIR induction in breast cancer cells, we observed a significant enrichment of these genes on the DCG category (P-value = 6.35 × 10−5; hypergeometric)." (PMID 26029238, 2015). "Some evidence shows that suppression of miR-7 by HOTAIR can mediate EMT progression in breast cancer." (PMID 25859406, 2015). "The results showed that the HOTAIR levels in breast cancer were significantly higher than those in normal women (p = 0.0007)." (PMID 25928008, 2015). "In this followup study, they observed a trend of higher HOTAIR expression in the metastatic than in the primary breast cancers." (PMID 25739705, 2015). "Further understanding the contributions of the cross talk among the signaling pathways governed by EGFR, c-ABL, β-catenin, and HOTAIR is expected to shed new light to the diagnosis, treatment, and prognosis of breast cancer." (PMID 25883211, 2015). "Intriguingly, the Breast Cancer 1, early onset gene (BRCA1), whose mutations are responsible for a number of inherited breast cancers, inhibits the interaction between PRC2 and HOTAIR by competing with HOTAIR for binding to EZH2." (PMID 25774169, 2015). "The current study investigated the role of HOTAIR expression in relation to nodal metastases in a breast cancer TMA cohort." (PMID 25739705, 2015). "In conclusion, our findings offer important new insights into the ability of estrogenic GPER signaling to increase the HOTAIR level by inhibiting miR-148a in breast cancer." (PMID 25928008, 2015). "In another breast cancer study it was shown that HOTAIR is regulated by oestradiol in estrogen receptor dependent manner." (PMID 25954300, 2015). "HOTAIR plays an important role in the regulation of cancer cell proliferation and cancer invasion in breast cancer." (PMID 25928008, 2015). "HOTAIR was strongly increased in primary tumors and metastases of breast cancer patients, with expression levels positively correlated with a poor survival rate." (PMID 26252651, 2015). "The up-regulation of HOTAIR has been reported in both estrogen receptor (ER) positive and triple-negative (TN) breast cancer." (PMID 25928008, 2015). "We found that the miR-148a level was negatively correlated with the HOTAIR level in breast cancer patients." (PMID 25928008, 2015). "The results showed that HOTAIR expression was significantly up-regulated in the PBMCs (p = 0.0285) and tissues (p = 0.0048) from the migrated breast cancer patients." (PMID 25928008, 2015). "This study also demonstrated that HOTAIR knockdown induced apoptotic pathways in breast cancer cell lines and suggested estrogen receptors as coregulators for HOTAIR expression." (PMID 26448935, 2015). "The effects of HOTAIR overexpression on the phenotype of VM-CUB1 UC cells resembled those by overexpression of HOTAIR in breast cancer, gastric cancer and pancreatic cancer cells." (PMID 25994132, 2015). "In this study, we found that HOTAIR was increased in the peripheral blood mononuclear cells and cancer tissues from breast cancer patients, and was especially higher in patients with metastatic breast cancer." (PMID 25928008, 2015).
breast cancer (continued). "HOTAIR, a lincRNA which is part of the Hox gene cluster, proved to be related to breast cancer progression." (PMID 25628894, 2015). "In the present study, we found that HOTAIR was increased in breast cancer patients, and was especially higher in migrated breast cancer." (PMID 25928008, 2015). "In breast cancer, HOTAIR plays also a promoter role, overexpression of HOTAIR being associated with metastasis and poor overall survival." (PMID 26703550, 2015). "Our findings rather fit well with the observation in breast cancer, where strongly increased HOTAIR expression was more prominent at higher stages and even more in metastases." (PMID 25994132, 2015). "Researchers working on human breast cancer cells have shown that diethylstilbestrol and bisphenol-A can upregulate the expression of HOTAIR in these cells." (PMID 25859406, 2015). "Taken together, we are reporting a new mechanism of E2 regulating HOTAIR expression in breast cancer." (PMID 25928008, 2015). "The overexpression of HOTAIR is sufficient to promote invasion and metastasis of breast cancer cells by re-directing the activity of the PRC2 complex to hundreds of genes, including many metastasis suppressor genes." (PMID 25774169, 2015). "A previous study reported that increased expression levels of HOTAIR in primary breast cancer tumors was a prognostic factor for metastasis and death." (PMID 25411894, 2015). "As some regulatory effects of HOTAIR in breast cancer cells occurred only after stable transfection and long-term serial passaging, we generated clones of 5637 and VM-CUB1 stably overexpressing HOTAIR as well as vector controls." (PMID 25994132, 2015). "Enforced expression of HOTAIR in breast carcinoma cells induced genome wide retargeting of PRC2 and, as a result, altered H3K27 methylation and gene expression patterns, increased invasiveness, and metastasis." (PMID 25954300, 2015). "HOTAIR, a long non-coding RNA initially identified in breast cancer, was shown to be upregulated in a variety of carcinomas." (PMID 24953832, 2014). "An intriguing phenomenon observed in the seminal study of HOTAIR in breast cancer is that established breast cancer cell lines exhibit a much lower expression of HOTAIR than breast cancer tissues." (PMID 25491133, 2014). "Since its first link to metastasis in breast cancer, elevated expression of HOTAIR has been reported in at least 16 types of malignancies." (PMID 25491133, 2014). "It is known that HOTAIR expression in metastatic sites was higher than in primary sites for breast cancer." (PMID 24591352, 2014). "In breast cancer, HOTAIR expression is upregulated in both primary and metastatic tumors, and its expression in primary tumors is strongly correlated with later metastases, patient prognosis, and death." (PMID 25400658, 2014). "In breast cancer cells, estradiol activates the expression of HOTAIR via recruitment of histone methyltransferases mixed lineage leukemia proteins (MLL) to the HOTAIR promoter." (PMID 25491133, 2014). "Recently, increased levels of HOTAIR in primary breast tumors were shown to correlate with breast cancer invasiveness and metastasis." (PMID 25496320, 2014). "As exemplified in a breast cancer study simultaneous increase of HOTAIR and PRC2 has a greater correlation with poor survival than the increase of each marker alone." (PMID 25491133, 2014). "For example, lncRNA HOTAIR is overexpressed in breast cancer and overexpression of HOTAIR has been shown to drive breast cancer metastasis in vivo." (PMID 25268745, 2014). "One lncRNA, HOX antisense intergenic RNA (HOTAIR), has been shown to be dysregulated in many types of cancer, including breast cancer, colorectal cancer, and hepatoma." (PMID 25334066, 2014). "The discovery of HOTAIR as an independent prognostic factor in breast cancer was initially reported by Gupta and collaborators and later validated in another cohort." (PMID 25296969, 2014).
breast cancer (continued). "HOTAIR is aberrantly expressed in a variety of human cancers, including breast cancer, colorectal cancer, laryngeal squamous cell carcinoma, and liver cancer." (PMID 25157956, 2014). "Recent studies showed that HOTAIR is an independent prognostic factor of metastases in estrogen receptor (ER)-positive primary breast cancer." (PMID 25334066, 2014). "Prolonged exposure of human breast cancer MCF-7 cells to tumor necrosis factor-α (TNF-α) induces the expression of HOTAIR and EMT." (PMID 25491133, 2014). "An alternative mechanism for HOTAIR’s function in breast cancer is through competitive binding with tumor suppressor genes." (PMID 25400658, 2014). "The highly metastatic breast cancer cell line MDA-MB-231 showed a 4.77-fold upregulation of HOTAIR compared with MCF-7." (PMID 24775712, 2014). "As a novel molecule in the field of tumor biology, HOTAIR initially became well known for its involvement in primary breast tumors and breast cancer metastases, wherein elevation of HOTAIR promoted invasiveness and metastasis." (PMID 24775712, 2014). "HOTAIR expression was low in normal breast epithelia but high in primary breast cancer as well as metastatic lesions, HOTAIR expression level was a powerful predictor of patient outcomes." (PMID 23680400, 2013). "In breast cancer, the overexpression of HOTAIR increases metastatic potential both in vitro and in vivo." (PMID 23717443, 2013). "HOTAIR is proposed as an oncogene because its expression is elevated in several types of cancers and mediates invasion and metastasis of breast cancer cells." (PMID 23668363, 2013). "LncRNAs have been described that function as oncogenes, tumour suppressors or drivers of metastatic transformation, such as HOTAIR in breast cancer." (PMID 23887658, 2013). "HOTAIR increased breast cancer invasiveness and metastasis by inducing positive regulators of cancer metastasis (ABL2 SNAIL, LAMB3 and LAMC2) in a manner dependent on PRC2." (PMID 23936419, 2013). "HOTAIR has been demonstrated to be upregulated in breast cancer, hepatocellular carcinoma, pancreatic cancer, laryngeal squamous cell carcinoma and colorectal cancer." (PMID 23717443, 2013). "Recently HOTAIR was found to be crucial for cell growth and viability and that its knockdown induced apoptosis in breast cancer cells Moreover it was found that HOTAIR is transcriptionally induced by estradiol." (PMID 24129177, 2013). "It has been found that lncRNA HOTAIR is highly upregulated in breast cancer, hepatocellular carcinoma (HCC), colorectal cancer and gastrointestinal stromal tumors (GIST)." (PMID 23725405, 2013). "A metastatic breast carcinoma tissue microarray containing 110 metastatic lesions matched to 56 primary carcinomas on the first breast cancer microarray was used to determine the expression of both HOTAIR and EZH2 in the matched pairs." (PMID 23133536, 2012). "We have previously demonstrated that the expression level of lncRNA in the HOX locus, including HOTAIR, is a predictor of breast cancer metastasis." (PMID 23133536, 2012). "Lastly, using matched primary and metastatic breast carcinomas we determine if HOTAIR and EZH2 have increased expression in metastatic versus primary breast carcinoma." (PMID 23133536, 2012). "The well-studied HOX antisense intergenic RNA (HOTAIR), for example, is highly expressed in breast cancers and breast cancer metastases and plays a role in retargeting chromatin remodeling complexes." (PMID 21991387, 2011). "HOTAIR, for example, has only been described in breast cancer, while three lncRNAs PCGEM1, DD3 and PCNCR1 have been associated solely with prostate cancer." (PMID 21489289, 2011). "HOTAIR: Found in high levels in endometrial and cervical, breast cancers." (PMID 39912983, 2025). "In addition, lncRNA HOTAIR is upregulated in breast cancer tissues, and is a sponge for miR-129-5p as well as promotes breast cancer progression." (PMID 41219994, 2025).
breast cancer (continued). "HOTAIR single-nucleotide polymorphisms (SNPs) have been studied as potential cancer susceptibility sites and have been associated with an increased risk of human cancers, such as breast cancer (BC), esophageal squamous cell carcinoma, stomach cancer, lung cancer, and colorectal cancer." (PMID 40642606, 2025). "Moreover, higher levels of exo-lncRNA HOTAIR are associated with poor prognosis in breast cancer patients, and it can induce EMT of breast cancer cells and metastasis formation." (PMID 40496868, 2025). "A number of promising lncRNAs show altered expression in many tumor types, e.g., PCA3 (in prostate cancer), HOTAIR (breast cancer, laryngeal squamous cell carcinoma, cervical cancer, and urothelial bladder cancer), BCAR4 (colorectal cancer), and MALAT1 (non-small cell lung cancer)." (PMID 40002172, 2025). "Our findings emphasize the potential of the HMGA2 associated HOTAIR axis as a prognostic biomarker and therapeutic target, especially in ER negative, postmenopausal onset, and relapsed breast cancer." (PMID 40686703, 2025). "The dysregulated expression of HOTAIR in BRCA1 has been observed in breast cancer." (PMID 39997609, 2025). "As a result, CHEK1 and HOTAIR also served as oncogenic roles in breast cancer." (PMID 38561760, 2024). "Like other lncRNAs such as HOTAIR in breast cancer and MALAT1 in lung cancer, ST8SIA6-AS1 could interact with chromatin-modifying proteins to influence gene expression epigenetically." (PMID 39211393, 2024). "The same team also found that low concentrations of BPA and DES could significantly induce HOTAIR expression in breast cancer cells, suggesting that small-molecule compounds could regulate the levels of lncRNAs." (PMID 38688909, 2024). "For instance, the lncRNA PCA3 (Prostate Cancer Antigen 3) is used as a diagnostic marker for prostate cancer, and it can be easily found in urine samples; the lncRNA HOTAIR (HOX antisense intergenic RNA) is involved in hormone therapies resistant in breast cancer." (PMID 38095719, 2024). "Knocking down HOTAIR could offer a selective strategy for breast cancer treatment via repress a variety of carcinogenic pathways simultaneously." (PMID 38374003, 2024). "Through controlling miR-34a and subsequently SOX2, HOTAIR upregulation in CSCs isolated from breast cancer cells may be essential for maintaining self-renewal potential." (PMID 39170516, 2024). "Furthermore, upregulation of HOTAIR has been reported to suppress the expression of miR‐19, contributing to enhanced proliferation and invasion of breast cancer cells." (PMID 39347925, 2024). "For example, HOTAIR is highly expressed in breast cancer and may promote cell cycle progression by binding to cell cycle-related proteins, leading to excessive proliferation of cancer cells." (PMID 39479021, 2024). "Furthermore, HOTAIR is highly expressed in tamoxifen-resistant breast cancer patients compared to newly diagnosed patients before tamoxifen treatment." (PMID 38505593, 2024). "That means HOTAIR may have the chance to become a therapeutic target for the treatment of breast cancer." (PMID 39479021, 2024). "Additionally, reports have suggested that HOTAIR promotes the proliferation of breast cancer CSCs and influences stem cell proliferation and differentiation." (PMID 38267415, 2024). "HOTAIR negatively controlled miR-206 expression in medulloblastoma, colorectal, and breast cancers." (PMID 38334898, 2024). "Notably, a significant increase in HOTAIR expression was detected after 6 months of treatment in all patients with metastasis, as well as in all patients with locally advanced breast cancer and stage IV breast cancer." (PMID 38114755, 2023). "Furthermore, the differential expression fold of miR-1246 and HOTAIR revealed a strong positive correlation among breast cancer patients." (PMID 36865390, 2023).